INS (insulin)
Diseases named in the same sentence as INS in open-access papers (continued):
Sharing a sentence is not in itself a finding about the gene and the disease.
Hypoglycemia (continued). "Fifteen of the 31 (48%) remaining cats that presented non-hypoglycemic developed hypoglycemia within 12 h of receiving an initial dose of dextrose and insulin for the treatment of hyperkalemia." (PMID 36350735, 2022). "Classes that do not induce hypoglycemia should be used in preference to insulin, sulfonylureas, and glinides, unless individualized glycemic targets cannot be met otherwise (see Section 2.2.4." (PMID 34922811, 2022). "Therefore, this study assessed the rate of hypoglycemia incidence and level of glycemic control between NPH and premixed insulin regimens among patients with T2DM at the University of Gondar Comprehensive Specialized hospital (UoGCSH)." (PMID 36149907, 2022). "Then, once the fetus is born without the nutritional supply from the mother, high peripheral insulin levels can lead to neonatal hypoglycemia in the absence of glucose supplementation." (PMID 36530712, 2022). "The hyperactivity of pancreatic beta cells seemed unlikely to be responsible for hypoglycemia, as plasma insulin levels were not increased in dnPKAiEC mice." (PMID 36232721, 2022). "In the study, dapagliflozin 5 and 10 mg did not raise the incidence of hypoglycemia compared with insulin alone (OR = 0.94, 95% CI: 0.82 to 1.1 and OR = 0.98, 95% CI: 0.86 to 1.1)." (PMID 35872994, 2022). "Glucagon-like peptide-1 receptor agonists (GLP-1 RAs) are incretin mimetics that both stimulate glucose-dependent insulin release and suppress glucagon secretion, leading to reduced blood glucose levels without affecting defence mechanisms to hypoglycaemia." (PMID 36104712, 2022). "Automated insulin delivery shows great promise in helping patients achieve glycemic targets while mitigating hypoglycemia, but is not perfect nor universally accessible." (PMID 37745178, 2021). "Other patient-related factors (e.g., fear of hypoglycemia, weight gain or beliefs that insulin therapy is not efficacious, or fear that their quality of life will drop considerably) can contribute to therapeutic inertia." (PMID 34062938, 2021). "Administration of an insulin preparation was necessary; however, blood glucose was relatively well-controlled and no symptomatic hypoglycemia occurred." (PMID 34928447, 2021). "Hypoglycemia was not due to hyperinsulinemia, as fasting insulin levels were significantly reduced in both Rptorob−/− and Rptorob+/− mice compared to controls." (PMID 33551450, 2021). "Guidelines recommend that to prevent exercise-induced hypoglycaemia, patients with T1D must either reduce their basal insulin doses or consume carbohydrates without co-administration of insulin prior to commencing exercise." (PMID 33914197, 2021). "The recently developed receptor agonists for glucagon-like peptide-1 (GLP-1RAs), stimulate insulin secretion and reduce glycated hemoglobin levels without having side effects such as weight gain and hypoglycemia." (PMID 34131405, 2021). "Not considering insulin and treatment for hypoglycaemia, the mean number of prescribed drugs was 4.00 (SD 4.35)." (PMID 33608768, 2021). "Among insulin users, hypoglycemia and the many negative impacts experienced as a result of moderate, severe and nocturnal hypoglycemia in all aspects of life were considered a top priority outcome." (PMID 34507618, 2021). "We also found that such training in hypoxia required lower carbohydrate consumption within a training session and there was lower need for short-acting insulin dose reduction to prevent hypoglycemia, in comparison to normoxia (p > 0.05)." (PMID 34948667, 2021). "In individuals without diabetes, hypoglycemia is initially counteracted by increased glucagon secretion and suppression of endogenous insulin release." (PMID 34444787, 2021). "Hypoglycemia episodes may often be treatable with less CHO than clinical guidelines recommend during PLGS and closed-loop insulin delivery, where insulin suspension precedes hypoglycemia." (PMID 33535013, 2021).
Hypoglycemia (continued). "It is important to emphasize that these two latter improvements agreed with the absence of severe hypoglycemia for the one-year period, and that the cited benefits occurred whatever the baseline glycemic problem and the insulin delivery modalities." (PMID 34577338, 2021). "Suspension of insulin delivery in response to actual and forecasted hypoglycemia has improved quality of life and mitigated hypoglycemia without compromising glycemic control." (PMID 37745178, 2021). "The most highly ranked barriers to insulin therapy by physicians included the patient’s compliance, patient’s motive, dependence on others for insulin injection, hypoglycemia, patient’s socioeconomic status, occupation, and lack of follow-up." (PMID 34712538, 2021). "Meal intake induced an exaggerated immediate stimulation in insulin and C-peptide leading to hypoglycemic levels after 120 min in patients with hypoglycemia compared to patients without hypoglycemia." (PMID 33624213, 2021). "Interestingly, blood insulin levels trended lower in PKCβHep–/– mice relative to controls, but never reached a significant difference under either fasted or fed conditions, suggesting that hypoglycemia in PKCβHep–/– mice may not be caused by improvement in insulin sensitivity." (PMID 34622807, 2021). "The adrenal sympathetic nerve, unlike renal, lumbar, or muscle sympathetic nerves, is activated by hypoglycemia independent of elevated insulin levels and can be acutely recorded in anesthetized rats." (PMID 34444787, 2021). "As such, cortisol levels are not upregulated during hypoglycemia as a consequence of insulin injections, whereas epinephrine levels do increase, leading to elevated blood monocyte levels." (PMID 34091064, 2021). "During different insults of hypoglycemia, both increases and a lack of alterations in insulin-independent glucose transporter abundance (GLUT1 and GLUT3) have been described." (PMID 34948265, 2021). "Introduction of algorithms used to forecast future hypoglycemia based on CGM trends and insulin-on-board led to predictive low glucose suspend (PLGS), including the MiniMed 640G (Medtronic, Northridge, California) and the Basal-IQ system (Tandem Inc., San Diego, California)." (PMID 37745178, 2021). "It should also be noted that data on a number of important confounders, including hypoglycaemia awareness, family support, and type of insulin used, were not available for the analyses." (PMID 33452386, 2021). "Of further note, the affinity of proinsulin and PPI for the insulin receptor is much lower than that of insulin itself, thus minimizing undesirable metabolic side effects upon systemic absorption, e.g. hypoglycemia, which we did not observe." (PMID 34447366, 2021). "Therefore, stem cell therapy for β-cells can potentially improve glucose-stimulated insulin secretion, resulting in better control of the TIR and a reduction in the frequency of hypoglycaemia." (PMID 34202521, 2021). "Among the 803 insulin-treated patients without a hypoglycemia-related adverse event, MACE occurred in 124 (15.4%, P = 0.58)." (PMID 34158057, 2021). "Patients with SH had a lower incidence of hypoglycemia, independent of the three insulin schemes used (basal, bolus, or basal-bolus)." (PMID 34852895, 2021). "The biochemical mechanism by which hypoglycemia and high insulin levels can induce retinal damage is not completely understood." (PMID 34442032, 2021). "The weight gain was described as the second negative effect of intensive insulin therapy besides hypoglycemia." (PMID 34909088, 2021). "The findings highlighted that the levels of knowledge of hypoglycemia and insulin pen use were not optimal at baseline but were significantly improved after the health education intervention." (PMID 34497858, 2021). "The major reasons for not injecting insulin were fear of hypoglycemia (10.6%), the belief that insulin is not effective in achieving glycemic control (3.7%), forgetfulness (88%), and aichmophobia (1.9%)." (PMID 34826318, 2021).
Hypoglycemia (continued). "Insulinoma should be suspected in a patient with autonomic and/or neuroglycopenic symptoms, blood glucose <55 mg/dL and insulin levels not suppressed in the presence of hypoglycemia." (PMID 34199977, 2021). "Patients with these forms of neonatal diabetes can effectively transition off insulin onto high-dose sulphonylurea, and most achieve normoglycemia with no hypoglycemia, consistent with glucose-dependent insulin secretion." (PMID 33693776, 2021). "In the hypoxia group, patients reduced their dose of insulin with a meal before training to a lesser extent, which did not affect the incidence of hypoglycemia in this group." (PMID 34948667, 2021). "An additional explanation for the sex difference regarding insulin and TOC levels could be the different reactions of ucOC level to hypoglycemia dependent on sex." (PMID 35010988, 2021). "A significantly larger proportion of patients on IDegAsp achieved the HbA1ctarget of <7% (ADA goal) without confirmed hypoglycemia compared to those on basal insulin alone (43% vs. 25%, respectively, p < 0.01)." (PMID 34071359, 2021). "For physicians, the patient's treatment compliance, motive, dependence on others for insulin therapy, hypoglycemia, socioeconomic status, occupation, and lack of follow-up were the most highly ranked barriers to initiating insulin therapy." (PMID 34712538, 2021). "Additionally, diabetic patients at higher risk of developing hypoglycaemia might adopt over-compensatory behaviours in order to avoid the aversive symptoms of hypoglycaemic events, including treatment nonadherence (taking lower insulin dose) or skipping it." (PMID 34646639, 2021). "Adverse events related to hypoglycemia were more common in insulin-treated patients (n = 26, 3.1%) than in patients not treated with insulin (n = 11, 0.7%, P < 0.001)." (PMID 34158057, 2021). "Here, intranasal insulin was found to reduce blood sugar levels, an effect that lasted at least 4 hours without developing hypoglycemia." (PMID 34540446, 2021). "We used different indices for an estimation of insulin secretion capacity and insulin sensitivity, which did not indicate significant differences between patients with and without hypoglycemia regarding these parameters." (PMID 33624213, 2021). "Glycemic stability and a lower incidence of hypoglycemia also persisted following ICT regardless of insulin independence." (PMID 33573247, 2021). "Not considering insulin and treatment for hypoglycaemia, roughly one-quarter of individuals were taking five or more drugs by 40 years of age." (PMID 33608768, 2021). "The study reported that diabetic patients who were not on basal insulin therapy had increased odds of hypoglycaemia and this ration was greater for the selective beta‐blockers compared to carvedilol." (PMID 33855225, 2021). "Insulin and C-peptide levels were not significantly different between normoglycemic neonates and neonates who developed hypoglycemia." (PMID 34676825, 2021). "Nonetheless, the present study demonstrates that surgical ablation of the common hepatic artery is safe in our diet‐induced glucose‐intolerant dog model and does not amplify the effect of exogenous insulin on hypoglycemia." (PMID 33769710, 2021). "One of the negative side effects of insulin use, however, is that it can lead to dose overestimations and hypoglycemia." (PMID 34003799, 2021). "In the event of insulin-induced hypoglycemia in nondiabetic people, formidable counterregulatory hormone responses exist to restore euglycemia." (PMID 34003799, 2021). "Symptomatic hypoglycemia did not occur, glucose levels were well-controlled with insulin administration and HbA1c level was 6.3% at 2 months after surgery." (PMID 34928447, 2021). "The combination of basal insulin with a glucagon-like peptide 1 receptor agonist (GLP-1 RA) displayed the lowest GV and hypoglycemia in patients with T2DM, which might contribute to a reduction of cardiovascular outcome." (PMID 33413392, 2021).
Hypoglycemia (continued). "When reached the peak, insulin secretion will not increase indefinitely but decrease slowly, which improves the safety of use and reduces the side effects like hypoglycaemia." (PMID 33300675, 2021). "In another study, fear of hypoglycemia, the patient’s refusal of insulin therapy, lack of confidence in physicians, and needle injections were among frequently recognized barriers." (PMID 34712538, 2021). "Since we did not evaluate the proportion of basal bolus insulin, we were unable to identify this contribution to the prevalence of hypoglycemia in our population." (PMID 33905628, 2021). "We can conclude that a standardized bout of moderate-level hypoglycemia-inducing physical activity without previously provided preventive steps (decreased insulin dosing and extra portions of saccharides) led to hypoglycemia in all the participants." (PMID 34836420, 2021). "The current study provides a novel insight into the sympathoadrenal CRR to insulin-induced hypoglycemia under conditions of nutritional ketosis in healthy, nondiabetic rats." (PMID 34444787, 2021). "These drugs inhibit the reabsorption of glucose from the kidney; thus, they increase glycosuria, improve the glycemic index without affecting insulin release, and avoid hypoglycemia." (PMID 34722075, 2021). "Thus, the practice of using intensive insulin therapy to achieve tight glycaemic control among critically ill patients has not been justified by these studies given such practice may not improve mortality and can increase the risk of hypoglycaemia." (PMID 34277991, 2021). "The increase in the glucose level at 30 min of the OGTT was accompanied by a significant increase in insulin secretion at 60 min, without subsequent hypoglycaemia after an hour of observation (at 120 min)." (PMID 34903800, 2021). "One study in 9 patients with CFRD-FH+ used insulin pump therapy for 6 months achieving a significant reduction of HbA1c, fasting and postprandial blood glucose, without severe hypoglycemia events (evidence Moderate)." (PMID 34017312, 2021). "To exclude the possibility that StAR up-regulation and mimecan down-regulation are induced by insulin itself, rather than by insulin-induced hypoglycemia stress, we examined the StAR and mimecan mRNA levels after insulin stimulation in Y1 cells." (PMID 33971622, 2021). "Although adherence with insulin injections is the most important factor, diet and lifestyle may also significantly contribute to the risks for DKA and hypoglycaemia." (PMID 33452386, 2021). "The incidence of hypoglycemia has not been significantly lower in diabetic patients with improved blood glucose management and increased use of insulin." (PMID 34925792, 2021). "In this study, we observed that dapagliflozin as an adjunct to insulin significantly reduced basal and bolus insulin doses in T2D after 5-week treatment, with no weight changes and hypoglycemia." (PMID 34497852, 2021). "The robust increase in circulating FABP4 during hypoglycemia and its ability to restore normoglycemia may indicate a role for FABP4 as an additional insulin counterregulatory hormone." (PMID 34676825, 2021). "Glargine insulin in CFRD patients did not increase the risk of hypoglycemia when compared to NPH, and repaglinide does not increase the number of hypoglycemic events compared to regular insulin." (PMID 34017312, 2021). "Although hypoglycaemia was not previously reported during treatment with oral insulin, children <2 years of age have not been exposed to oral insulin." (PMID 33515070, 2021). "While hypoglycemia and weight gain are well-established side effects of insulin therapy, they were not the most important barriers in these studies." (PMID 34712538, 2021). "In that study, insulin effect was measured in non-diabetic and diabetic subjects where it was noticed that in non-diabetic subjects, hypoglycemia downregulated the production capacity of TNF-α." (PMID 34067027, 2021).
Hypoglycemia (continued). "Pancreatogenic diabetes is characterized by the absence of the major glucoregulatory hormones insulin and glucagon and instability and frequent hypoglycemia, and its management is crucial." (PMID 34067286, 2021). "Consequently, there is an unmet need for adjunctive treatment plus insulin in T1DM to meet the twin challenges of hyperglycemia and hypoglycemia." (PMID 33651228, 2021). "Reversely, several studies have not demonstrated an increased rate of hypoglycemia during intensive insulin therapy." (PMID 34909088, 2021). "The following results were obtained during an episode of hypoglycemia: glucose, 2.3 mmol/L; concomitant serum insulin, 13.52 (normal: 4.03-23.46) μIU/mL; C-peptide 4.25 (normal: 0.3-3.73) ng/mL; beta-hydroxybutyrate < 0.1 mmol/L." (PMID 32482020, 2021). "Despite several studies showing an increase in the frequency of hypoglycemia during and after exercise, many youth are not adjusting insulin for exercise." (PMID 34647896, 2021). "They concluded that 25% additional aspart-insulin for a HFHP breakfast significantly improved postprandial glycemia without hypoglycaemia." (PMID 34684559, 2021). "In all of our previous studies in the B6N substrain, we have never had to rescue a mouse because of hypoglycemia during insulin tolerance tests (ITTs) (M.E.K., personal observations)." (PMID 33172888, 2021). "None of the patients in the exenatide group developed hypoglycemia, while 10% of the insulin group patients developed symptomatic hypoglycemia." (PMID 34164242, 2021). "Not surprisingly, the active basal insulin dose and glycemic summary measures were the strongest predictors of near-term hypoglycemia." (PMID 33416883, 2021). "None of the babies were on insulin, and there was no clinical evidence of hypoglycaemia in these babies during any of these episodes." (PMID 31399480, 2020). "In our studies, GHRH neuron activation is blunted by repeated 2DG or insulin treatment, suggesting that decreased GHRH activity may contribute to impaired CRR with repeated hypoglycemia." (PMID 33148883, 2020). "Homeostasis model assessment for pancreatic beta-cell function (HOMA-beta) increased significantly with treatment (p < 0.05), and fewer insulin doses were required after the treatment, without increasing in hypoglycemia and urinary tract infection." (PMID 33299890, 2020). "We found that, in ITTs, the initial dose of insulin did not adequately induce hypoglycemia (blood glucose value below 2.2 mmol/L or below 2.6 mmol/L with a 50% reduction from baseline) in 57.8% (32/56) patients." (PMID 32328036, 2020). "In some patients, insulin levels are often not increased at the time of hypoglycemia, because of the periodic release of insulin, which is missed by measuring a single serum sample." (PMID 31840185, 2020). "We therefore established a model in non-diabetic rats to study the effect of sustained insulin-induced hypoglycaemia on foetal skeletal development." (PMID 32221393, 2020). "None of these patients went home on Insulin, one on no medication, and six required medical treatment for ongoing hypoglycemia." (PMID 33108363, 2020). "Initial hypoglycemia screening revealed hyperinsulinemia with no ketonemia present (blood glucose 29 mg/dL, insulin 9.03 mU/L, C-peptide 2.34 μg/L)." (PMID 33275114, 2020). "In the absence of co-administration of insulin or insulin-stimulating drugs, metformin per se rarely induce hypoglycemia." (PMID 33693008, 2020). "Analogously, compared with placebo, lixisenatide added to basal insulin significantly reduced GV and PPG excursions without increasing the risk of hypoglycemia." (PMID 32622354, 2020). "In a clinical trial of intranasal insulin, it was well tolerated, and no subject exhibited hypoglycemia or other safety concerns." (PMID 32971941, 2020). "The MCD diet induced hypoglycemia with no change in insulin levels; therefore, the HOMA-IR index was not affected." (PMID 33374541, 2020).